VEGFA (vascular endothelial growth factor A)
Diseases named in the same sentence as VEGFA in open-access papers (continued):
Sharing a sentence is not in itself a finding about the gene and the disease.
Hyperglycemia (397 papers, 2007 to 2026). An increased concentration of glucose in the blood. "They explored impaired Trx activity resulting from elevated plasma glucose levels linked to hyperglycemia, which are known to adversely affect endothelial cell function, and diminish responsiveness to vascular endothelial growth factor-A (VEGF-A)." (PMID 41129928, 2025). "Our previous study showed that lncRNA H19 suppression protected the endothelium against hyperglycemia-induced inflammation and oxidative stress by upregulating miR-29b expression and downregulating VEGFA expression, which caused the activation of the AKT/eNOS pathway in endothelial cells." (PMID 35890121, 2022). "In summary, our findings underscore the therapeutic potential of miR-205-5p in mitigating hyperglycemia-induced VEGFA overexpression and pathological angiogenesis." (PMID 40002404, 2025). "In both ARPE-19 cells and diabetic mice, high hyperglycaemia dramatically increased VEGFA expression while decreasing miR-205-5p levels." (PMID 41464680, 2025). "Recent studies suggest that hyperglycemia can induce epigenetic modifications affecting miR-205-5p transcription, which in turn disrupts its regulatory functions on VEGFA." (PMID 40002404, 2025). "miR-205-5p modulates insulin sensitivity by targeting FOXO1, and its downregulation under hyperglycemia disrupts normal insulin signaling, promoting metabolic dysregulation and increased VEGFA expression." (PMID 40002404, 2025). "In the presence of hyperglycemia, the oxygen-carrying capacity of erythrocytes is lower than normal, and the resulting hypoxia activates HIF-lα, which causes an increase in VEGFA production." (PMID 38883603, 2024). "The researchers indicated that upregulation of miRNA‐16‐5p in hUCMSCs-Exos suppress VEGFA levels and provides protection to podocytes against the detrimental effects of apoptosis and hyperglycemia, both in vitro and in vivo." (PMID 38632264, 2024). "In support of enhanced angiogenesis by metformin, we found that although the concentration of VEGFA was progressively increased under hyperglycemia–hypoxia it was further enhanced following metformin." (PMID 26861446, 2016). "Metformin increased in vitro angiogenesis under hyperglycemia–hypoxia and augmented the expression of VEGFA." (PMID 26861446, 2016). "The results showed that while hyperglycemia did not cause significant changes, PA and PA + G25 induced apoptosis-related cell death and significantly increased the expression of VEGFA, VEGFR2, HIF-α, and SP1." (PMID 42278667, 2026). "Hyperglycemia upregulates VEGFA expression levels, leading to a decreased expression of miR-205-5p." (PMID 40002404, 2025). "SalB inhibits the expression of IGFBP3, triggering the vascular endothelial growth factor receptor 2 (VEGFR2)/vascular endothelial growth factor A (VEGFA) pathway to enhance ventricular remodeling, angiogenesis, and collagen deposition linked to hyperglycemia, ultimately protecting cardiac function." (PMID 39139645, 2024). "In series, hyperglycemia induces the upregulation of VEGFA and increases capillary density." (PMID 31487015, 2019). "The CM from CD34+ cells treated with metformin displayed augmented levels of VEGFA either under euglycemia (1.6-fold, p = 0.008), euglycemia combined with hypoxia (1.4-fold, p = 0.037), and hyperglycemia combined with hypoxia (1.2-fold, p = 0.037) compared with the metformin-untreatedcondition." (PMID 26861446, 2016). "Early blood retinal barrier (BRB) dysfunction induced by hyperglycemia was related to increased pro-inflammatory activity of phospholipase A2 (PLA2) and the upregulation of vascular endothelial growth factor A (VEGF-A)." (PMID 33065984, 2020). "However, hyperglycemia induces systemic disruption of physiological functions, such as angiogenesis, by suppressing the expression of various crucial angiogenic factors, such as the vascular endothelial growth factor-A (VEGF-A) and the platelet-derived growth factor-BB (PDGF-BB)." (PMID 31474865, 2019).
Hyperglycemia (continued). "We confirmed in our in vitro model, as it was shown in clinical studies, that hyperglycemia alone increased VEGFA but downregulated VEGFR-2 gene expression, neither of which were affected by metformin." (PMID 26861446, 2016). "However, the pro-angiogenic factor VEGFA was found to be significantly increased in CM collected from CD34+ cells treated with hyperglycemia (2.0-fold, p < 0.001) versus euglycemia, whereas no change was observed under hyperglycemia combined with hypoxia for 3 h versus hyperglycemia." (PMID 26861446, 2016).
renal cell carcinoma (361 papers, 2002 to 2026). "Of note, expression of TLS-polymerases correlates with VEGFA (primary HIF1α target) in a database of renal cell carcinoma, a cancer which accumulates HIF1α." (PMID 39468223, 2025). "A systematic review and differentiation of TFEB/6p21/VEGFA-amplified renal cell carcinoma and TFEB-translocated renal cell carcinoma in clinicopathological, histological, immunophenotypic, and molecular genetic features was performed." (PMID 38730456, 2024). "Whole-exome molecular genetic analysis of TFEB/6p21/VEGFA-amplified renal cell carcinoma has enhanced our understanding of this type of tumor." (PMID 38730456, 2024). "The first case of TFEB/6p21/VEGFA-amplified renal cell carcinoma with genomic instability was reported, presenting a new outlook on the treatment and prognosis of this tumor." (PMID 38730456, 2024). "TFEB/6p21/VEGFA-amplified renal cell carcinoma (RCC) is rare and difficult to diagnose, with diverse histological patterns and immunohistochemical and poorly defined molecular genetic characteristics." (PMID 38730456, 2024). "For the first time, the molecular genetics of TFEB/6p21/VEGFA-amplified renal cell carcinoma were completely and systematically characterized by exon sequencing." (PMID 38730456, 2024). "Then, through immunohistochemical analysis and an extensive literature review, we differentiated the patient’s tumor from various types of renal cancer and diagnosed it as TFEB/6p21/VEGFA-amplified renal cell carcinoma." (PMID 38730456, 2024). "A previous study showed that miR-205-5p overexpression suppressed the growth and EMT of renal cell carcinoma (RCC) cells by targeting the VEGFA and PI3K/Akt signaling pathways, thus serving as a tumor suppressor in RCC." (PMID 37400770, 2023). "For example, circTLK1 can bind to miR-136-5p to regulate CBX4 and VEGFA expression, thus promoting oncogenesis and the development of renal cell carcinoma." (PMID 35654787, 2022). "miR-299-3p inhibited cell proliferation and motility and induced apoptosis in renal cell carcinoma by directly targeting VEGFA." (PMID 32616068, 2020). "Of note, it has been demonstrated that renal cell carcinomas showing TFEB amplification harbor concurrent vascular endothelial growth factor A (VEGFA) gene amplification." (PMID 31382581, 2019). "Hypermethylation of the VHL promoter in renal cell carcinoma has been correlated with increased HIF1a expression, and deletion of miR-23b has been reported to reduce HIF1a and VEGFA expression via its targeting of VHL." (PMID 23560444, 2013). "In addition to its role in angiogenesis, VEGFA also contributes to key aspects of tumorigenesis in several kinds of malignancies, including renal cell carcinoma, lung cancer, and colorectal cancer." (PMID 38169627, 2024). "Then, we used ComiRNet, a web-based system, to assess the possible targets of miR-106a-5p, and we selected the top ten possible targets from ComiRNet and overlapped them with the renal cell carcinoma gene set from Diana miRPath; it happened when the VEGFA is the only overlapped gene." (PMID 33224312, 2020). "Preclinical studies have reported that VEGFA is overexpressed in patients with RCC, and reducing its expression may be a new means of clinical treatment for renal cell carcinoma." (PMID 38416262, 2024). "Further, renal cell carcinomas and epithelial ovarian carcinomas showed a correlation between GPR4, VEGFA and microvascular density." (PMID 36611126, 2023). "As for the regulated targets in the renal cell carcinoma pathway, TGFB1, EPAS1, HIF1A, VEGFA, KRAS, and PIK3CA regulated by miR-140 have been reported to interfere with KIRC." (PMID 35528546, 2022). "Hub genes in the ‘Renal cell carcinoma pathway’ based on PPI analysis, such as PIK3CA, VEGFA, and PIK3CB, were noted and have also been observed to play vital roles in ccRCC." (PMID 31443717, 2019).
renal cell carcinoma (continued). "PPI networks were also analyzed for the genes involved in the ‘Renal cell carcinoma pathway,’ and several hub genes, such as PIK3CA, VEGFA, and PIK3CB were noted." (PMID 31443717, 2019). "Currently, five drugs targeting VEGFA (bevacizumab) or its receptors (sunitinib, sorafenib, pazopanib and axitinib) were approved by FDA for the treatment of renal cell carcinoma (RCC)." (PMID 27222660, 2016). "Using the TCGA RNA-Seq dataset, we found that while two key pro-angiogenic ligands, VEGFA and PGF, were up-regulated in renal cell carcinoma, they were down-regulated in primary prostate adenocarcinoma (b for prostate, f for kidney)." (PMID 26341082, 2015). "Downstream hypoxia/HIF targets have shown promise in other cancers, including VEGFA in various cancers and GLUT1 in renal cell carcinoma." (PMID 25347326, 2014). "VEGFA, KDR, LYN, CD3E and LOX are among those factors that are not identified by DIAMOnD but have a renal cell carcinoma associated literature support." (PMID 29861861, 2018).
myocardial infarction (327 papers, 2007 to 2026). Gross necrosis of the myocardium, as a result of interruption of the blood supply to the area, as in coronary thrombosis. "Mechanically, tRF HC83 directly binds to MIAT (myocardial infarction-associated transcript) to down-regulate its expression and leads to the subsequent up-regulation of vascular endothelial growth factor A (VEGFA) expression." (PMID 40001986, 2025). "The aim of our study was to investigate the association between the VEGFA polymorphism rs2010963 and myocardial infarction in patients with type 2 diabetes, as well as the expression of VEGFA." (PMID 39766291, 2024). "The aim of this study was to investigate an association between the rs2010963 polymorphism of the VEGFA and myocardial infarction in patients with type 2 diabetes." (PMID 39766291, 2024). "For example, intramyocardial injection of synthetic modified RNA encoding human vascular endothelial growth factor A (VEGF-A) markedly improved heart function and enhanced survival in a myocardial infarction model in mice." (PMID 30544622, 2018). "It has been shown that modified RNA encoding human vascular endothelial growth factor-A (VEGF-A) led to marked improvement in heart function in a mouse myocardial infarction model." (PMID 25930950, 2015). "For instance, in cardiovascular diseases, the ginseng-derived tRF-hc83 binds to the lncRNA myocardial infarction associated transcript (MIAT) through base complementary pairing, inhibiting its interaction with VEGFA mRNA." (PMID 41550494, 2026). "miRNA-448 expression significantly increased in myocardial infarction rats, and miRNA-448/vascular endothelial growth factor A (VEGFA) suppressed the fatty acid synthase (FAS)/FAS-L signaling pathway against cardiomyocyte hypoxia injury." (PMID 40666187, 2025). "In a pre-clinical study of myocardial infarction, exosomal transfer of miR-486-5p increased vascular endothelial growth factor (VEGFA) signaling and enhanced cardiac angiogenesis." (PMID 38739452, 2024). "In animal models of ventricular remodelling after acute myocardial infarction, up‐regulation of VEGFA expression reduces left ventricular remodelling and improves cardiac function." (PMID 37603612, 2023). "Studies have found that VEGFA plays a key role in triggering cardiac angiogenesis after acute myocardial infarction, but these studies are still limited to animal experiments." (PMID 37457560, 2023). "Here, we used microsphere+CS-EPC-EVs to gradually release highly bioactive EVs, which ensures sustained delivery of sufficient active factors (SDF-1 and VEGFa) in the myocardial infarction area." (PMID 37055411, 2023). "In this context, FGF2 and VEGFA (Vascular endothelial growth factor A) secreted by EPDCs have been described to increase vessel density after myocardial infarction in a mouse model." (PMID 37754805, 2023). "The TF E2F8 regulates angiogenesis through activation of VEGFA in cooperation with HIF-1α19, while ABCG2 is associated with the cardiac repair of myocardial infarction and ECs survival." (PMID 35079076, 2022). "The expression of TNFα and iNOS was increased while the expression of VEGFA was reduced in the myocardial infarction group." (PMID 35548775, 2022). "Puerarin accelerated cardiac angiogenesis, improves cardiac function, and reduced myocardial infarction in a rat model by upregulating VEGFA, Angiopoietin-1(Ang-1), and Angiopoietin-2(Ang-2)." (PMID 30402122, 2018). "Future in vivo studies using myocardial infarction animal models are therefore essential to confirm whether Quercetin truly exerts cardioprotective effects by modulating VEGFA, PTK2, and GGT1, as predicted in our bioinformatic and molecular docking analyses." (PMID 41573742, 2025). "Vascular endothelial growth factor A (VEGFA), could promote vascularization after acute myocardial infarction (AMI) by enhancing ROS generation and autophagy mediated by ER stress." (PMID 37858115, 2023).
myocardial infarction (continued). "In diabetic rats, puerarin also reduced the myocardial infarction area via a reduction of oxidized stress, an inhibition of NF‐κB inflammation, and a potential rise in vascular endothelial growth factor A (VEGFA) mediated angiogenesis, subsequently greatly improving cardiac performance." (PMID 34964013, 2021). "Furthermore, the oxidative stress induced vascular permeability factor VEGFA secretion, which was related to increased myocardial infarctions." (PMID 33224271, 2020). "Also, increased production of Vascular Endothelial Growth factor A (VEGF-A) in the ischemic myocardium model of acute myocardial infarction (AMI) in mice can induce angiogenesis through ROS-ER stress-autophagy pathway in vascular endothelial cells." (PMID 31428311, 2019). "Lung delivery of surfactant protein B (SP-B) mRNA protected mice from respiratory failure, whereas myocardial injection of RNAiMAX-formulated mRNA, encoding human vascular endothelial growth factor A (VEGF-A), improved heart regeneration after myocardial infarction in mice." (PMID 28655327, 2017). "In contrast, VEGFA (0.919; 0.847–0.998; P = 0.044), KIT (0.754; 0.575–0.988; P = 0.041), TNF (0.881; 0.796–0.974; P = 0.014), CTNNB1 (0.920; 0.858–0.986; P = 0.018), and GGT1 (0.887; 0.796–0.989; P = 0.030) were associated with lower risk of myocardial infarction." (PMID 41573742, 2025). "Moreover, several beneficial effects of Dan Shen in HF prevention include an anti-cardiac hypertrophic effect, reducing adriamycin-induced cardiomyopathy, and improving cardiac angiogenesis and ejection function by modulating the HIF1α/VEGFA signaling pathway after myocardial infarction." (PMID 35898268, 2022). "Furthermore, the rs699947 VEGFA polymorphism is associated with collateral circulation in CAD patients and myocardial infarction risk in patients with rheumatoid arthritis as well as may affect the antihypertensive responses to enalapril." (PMID 28811677, 2017). "Besides this cellular model of arrhythmia, several studies had announced puerarin could accelerate cardiac angiogenesis and improve cardiac function of myocardial infarction rats by upregulating VEGFA, Ang-1 and Ang-233." (PMID 27762288, 2016). "In myocardial infarction (MI), tRF-hc83 binds to a specific region of lncRNA MIAT, inhibiting MIAT's adsorption of VEGFA mRNA and thereby releasing MIAT's suppression of VEGFA translation." (PMID 41550494, 2026). "Vascular endothelial growth factor-A (VEGF-A), a key mediator of angiogenesis, was increased in patients after myocardial infarction and correlated with high concentrations of inflammatory cytokines." (PMID 35877573, 2022). "Regulation of Vascular Endothelial Growth Factor A (VEGFA) levels is important for many gene therapy applications and has been under development for the treatment for conditions such as myocardial infarction and peripheral arterial disease." (PMID 35358280, 2022). "However, in ischemic myocardium model of acute myocardial infarction (AMI) in mice, ROS-ER stress/autophagy axis promotes angiogenesis in cooperation with vascular endothelial growth factor A (VEGF-A) in endothelial cells." (PMID 32426106, 2020). "We speculate that one of the reasons for the formation of vascular structure by recruited EPCs on Day 7 after myocardial infarction may be related to the continuous release of SDF-1 and VEGFa from EVs, resulting in increased EPCs homing with increased differentiation." (PMID 37055411, 2023). "Vascular endothelial growth factor-A (VEGFA) plays a protective role in ischemic heart disease and myocardial infarction (MI) by inducing angiogenesis." (PMID 32733273, 2020).